APOE (apolipoprotein E)
Diseases named in the same sentence as APOE in open-access papers (continued):
Sharing a sentence is not in itself a finding about the gene and the disease.
Alzheimer disease (continued). "The role of cerebral hypoperfusion injury in carriers of the apolipoprotein E-ε4 (APOE4) risk gene for Alzheimer’s disease (AD) and dementia is less established." (PMID 40220152, 2025). "Much of Alzheimer's disease (AD) risk is explained by age, apolipoprotein E (APOE) genotype, and sex." (PMID 40883957, 2025). "While APOE ε4 status is associated with a younger age-of-onset in late-onset Alzheimer’s disease and familial cases of AD, its role in sporadic cases of AD is less clear." (PMID 39825484, 2025). "Previous studies have shown that the APOE ε2 isoform is associated with a decreased risk of developing Alzheimer’s disease (AD) dementia." (PMID 40382659, 2025). "The APOE gene encodes a key lipid transport protein and plays a central role in Alzheimer’s disease (AD) pathogenesis." (PMID 40631171, 2025). "While APOE ε4 is recognized as a genetic risk factor for Alzheimer’s disease (AD), its frequency among C9orf72 expansion carriers with clinically and pathologically confirmed AD was almost equally represented in relation to other alleles." (PMID 41149812, 2025). "The functional consequences of the largest genetic risk factor for late onset Alzheimer’s disease (AD), the ε4 variant of the apolipoprotein E (APOE) gene, and how they drive AD pathogenesis remain poorly understood." (PMID 40709278, 2025). "The APOE ε4 genetic variant is the strongest genetic risk factor for late-onset Alzheimer’s disease (AD) and is increasingly being implicated in other neurodegenerative diseases." (PMID 40665049, 2025). "The APOE4 allele of the Apolipoprotein E (APOE) gene raises the likelihood of amyloid plaque buildup and neural toxicity, so one of the most important genetic risk factors for Alzheimer’s disease (AD)." (PMID 40430848, 2025). "Apolipoprotein E4 (ApoE4) is associated with an increased risk of Alzheimer’s disease (AD), depression, and anxiety, which were reported to improve after the administration of metformin." (PMID 39833961, 2025). "Alzheimer’s disease (AD) risk and progression are significantly influenced by APOE genotype with APOE4 increasing and APOE2 decreasing susceptibility compared to APOE3." (PMID 40898377, 2025). "Apolipoprotein E (ApoE) variants are central to Alzheimer’s disease (AD), Lewy body dementia (LBD) and Niemann-Pick disease type C (NPC)." (PMID 40301465, 2025). "Apolipoprotein E (ApoE) polymorphisms modify the risk of Alzheimer’s disease with ApoE4 strongly increasing and ApoE2 modestly decreasing risk relative to the control ApoE3." (PMID 39666759, 2024). "A well-known gene that influences the risk of Alzheimer’s disease is the apolipoprotein E (APOE) gene." (PMID 39768823, 2024). "The partition of Alzheimer’s disease genetic risk into APOE-related and polygenic risk beyond APOE is a simplification in this analysis." (PMID 38820112, 2024). "Second, we partitioned the genetic risk in Alzheimer’s disease into two components: APOE and other top variants combined into a single polygenic risk score." (PMID 38820112, 2024). "The exact mechanisms by which APOE ɛ4 and other genetic variants influence Alzheimer’s disease risk are the subject of extensive research, and are the focus of this study by Altmann and colleagues." (PMID 39018494, 2024). "Previous studies have shown that the APOE ε4 allele can be regarded as a genetic risk factor for Alzheimer’s disease and dementia." (PMID 38792885, 2024). "The APOE4 polymorphism of apolipoprotein E (APOE) is the largest genetic risk factor for late-onset Alzheimer’s disease (LOAD)." (PMID 38206365, 2024). "Regarding our genetic analysis, we only included the presence of the ApoE ε4 allele, as it is the only one for which there is consensus as a risk factor in developing Alzheimer's disease." (PMID 39498389, 2024). "It has been demonstrated that the apolipoprotein E (ApoE) 4 polymorphism was more common in patients with Alzheimer’s disease and H. pylori infection than in uninfected patients." (PMID 39202269, 2024).
Alzheimer disease (continued). "Apolipoprotein E, which has long been considered a high-risk factor for late-onset Alzheimer’s disease, is strongly regulated in both these murine and human clusters." (PMID 38542077, 2024). "Apolipoprotein E−/− (ApoE−/−) mice, which lack the gene encoding ApoE, are a well-established model for assessing Alzheimer’s disease due to their susceptibility to these neuropathological features." (PMID 39583389, 2024). "The APOE (Apolipoprotein E) gene is significantly associated with cognitive function and neurodegenerative diseases, particularly Alzheimer's disease." (PMID 39055052, 2024). "Among the ε2–ε4 polymorphic alleles, the ε4 allele of APOE gene (APOE4) is the strongest genetic risk factor for late-onset Alzheimer’s disease (AD)." (PMID 39468688, 2024). "APOE gene variants are associated with Alzheimer’s disease through mechanisms involving amyloid β metabolism, tau pathology, lipid metabolism, neuroinflammation, vascular factors, and gene-environment interactions." (PMID 38790930, 2024). "The APOE-ɛ4 gene and Alzheimer’s disease polygenic risk scores independently influenced atrophy and synergistically influenced white matter lesions." (PMID 39229494, 2024). "Third, this SNP is biologically compelling as it encodes the ApoE-Є4 allele, which has been associated previously with a shorter lifespan and several common age-related conditions, including Alzheimer’s disease and ischemic heart disease." (PMID 39286457, 2024). "The study identified the presence of two well-known APOE single nucleotide polymorphisms (SNPs) associated with Alzheimer’s disease: rs429358 (ε4 allele) and rs7412 (ε2 allele)." (PMID 38790930, 2024). "It has been elucidated that the apolipoprotein E (APoE) e4 allele has been interlinked with susceptibility to Alzheimer’s disease and dementia." (PMID 39338207, 2024). "The better-known genetic risk factor in late-onset Ad is the presence of the ε4 allele of the apolipoprotein E gene, although the biochemical networks that affect late-onset Ad comprise a broad spectrum of metabolic pathways." (PMID 38412549, 2024). "We also apply the platform to investigate the role of APOE- ε4, a risk variant for Alzheimer’s Disease, in its effect on neuronal survival." (PMID 37163077, 2024). "Hereditary autosomal dominant forms of Alzheimer’s Disease (AD) and Parkinson’s Disease (PD) are associated with mutations in APOE, as well as mutations in SNCA and LRRK2, respectively." (PMID 38510848, 2024). "For instance, in Alzheimer’s disease, variations in the APOE gene are associated with differences in response to certain drugs, such as cholinesterase inhibitors, which are commonly prescribed to slow cognitive decline." (PMID 39759457, 2024). "The apolipoprotein E ɛ4 allele is the primary genetic risk factor for the sporadic type of Alzheimer’s disease." (PMID 38384997, 2024). "Further benefits on cerebrospinal fluid beta-amyloid were also demonstrated in APOE-ε4 allele carriers with Alzheimer’s disease." (PMID 38803456, 2024). "Aging and apolipoprotein E4 (APOE4) are the two most significant risk factors for late-onset Alzheimer’s disease (LOAD)." (PMID 39769453, 2024). "Across all CU individuals and Alzheimer’s disease participants, male sex was associated with lower pDMN connectivity (β = −0.11, P = 0.01) and APOE ɛ;4 carriers had lower vDMN connectivity (β = −0.06, P = 0.05) and higher NFQ (β = 0.21, P = 0.03)." (PMID 38444909, 2024). "In contrast, APOE ε4, characterized by arginine at both positions, is reported to increase the risk of atherosclerosis, Alzheimer’s disease, and other neurodegenerative conditions." (PMID 38674156, 2024). "The isoform E4 of the Apolipoprotein E (ApoE) represents one of the strongest genetic risk factors for late-onset Alzheimer’s disease (AD)." (PMID 39596098, 2024).
Alzheimer disease (continued). "The APOE ε4 allele has been associated with a higher accumulation of amyloid plaques and neurofibrillary tangles, hallmark features of Alzheimer's disease, which contribute to accelerated cognitive decline." (PMID 39392181, 2024). "It has been proved that allele ε4 of the ApoE gene encoding the apolipoprotein E is a major genetic risk factor for Alzheimer’s disease (AD)." (PMID 38612605, 2024). "The PEX6 missense variant, rs1129187, has been associated with Alzheimer’s disease in APOE ε4 carriers." (PMID 38674429, 2024). "A search in the GWAS Catalog database revealed pleiotropic associations of the APOE variant with lipid traits and Alzheimer disease, and a multitude of other phenotypes." (PMID 38716647, 2024). "The APOE gene, especially its “4” allele, which encodes the APOE protein, is the most significant genetic susceptibility factor for Alzheimer’s disease." (PMID 39596378, 2024). "The APOE ε4 allele, widely recognized as the primary risk factor for Alzheimer’s disease (AD), induces broad molecular and cellular changes linked to AD phenotypes, prominently enhancing amyloid-beta (Aβ) deposition in the brain." (PMID 39185458, 2024). "APOE genotypes have well-established risk-modifying properties in Alzheimer’s disease (AD) and appear to be implicated in the pathology of aS-pathies, as well." (PMID 38339074, 2024). "The ε2, ε3 and ε4 alleles of the APOE gene make up the proteins of three ApoE isoforms, ApoE2, ApoE3, and ApoE4, in which E3 is a protective factor and E4 is a risk factor for Alzheimer’s disease." (PMID 39062868, 2024). "Alzheimer’s disease risk biomarkers were measured in cerebrospinal fluid and assessed by genotyping [apolipoprotein E (APOE) ε4 variant]." (PMID 39154864, 2024). "TOMM40 Sigis attributed to APOE RS 429358-T, while APOE allele-specific variants increase nonalcoholic fatty liver disease and obesity but decrease the risk of Alzheimer’s disease and myocardial infarction." (PMID 39619635, 2024). "Linear mixed models were used to assess the main effects of coffee and tea consumption, as well as their interactions with Apolipoprotein E (APOE) genetic risk—the strongest genetic risk factor for Alzheimer’s disease (AD)." (PMID 39770924, 2024). "Apolipoprotein E (APOE) ε4 allele is the strongest genetic risk factor for late onset Alzheimer’s disease (AD)." (PMID 39482741, 2024). "Recent studies have shown that ApoE subtypes, which are biomarkers for Alzheimer’s disease, are associated with AMD." (PMID 39767734, 2024). "Apolipoprotein E (APOE), a crucial protein in lipid transport and brain injury repair, is implicated in Alzheimer's disease risk." (PMID 38725077, 2024). "Polymorphisms in the APOE gene have been linked to an elevated risk of various diseases, such as Alzheimer’s disease and cardiovascular diseases, and even skeletal muscle phenotypes." (PMID 39359931, 2024). "In individuals with the apolipoprotein E genotype ε2/ε3, males have a higher risk of developing Alzheimer’s disease than females." (PMID 38481441, 2024). "A study on late-onset Alzheimer’s disease focusing on protein–protein network interactions revealed eight genes with strong associations: APOE, SORL1, APOC1, CD33, CLU, TOMM40, CNTNAP2, and CACNA1C." (PMID 39228919, 2024). "The E4 allele of APOE (APOE4) is the strongest genetic risk for Alzheimer’s disease, yet in glaucoma the presence of APOE4 appears to be neuroprotective." (PMID 39015474, 2024). "Advanced age is the most important risk factor for Alzheimer’s disease (AD), and carrier-status of the Apolipoprotein E4 (APOE4) allele is the strongest known genetic risk factor." (PMID 38941766, 2024). "Here, we expand upon this analysis by investigating the impact of APOE ε4 genotype on the association between iron and Alzheimer’s dementia diagnosis (confirmed by clinical and pathological characterization; 608 subjects)." (PMID 35484240, 2024).
Alzheimer disease (continued). "The main genetic risk factor for Alzheimer’s disease (AD) is the apolipoprotein E ε4 allele (APOE4)." (PMID 39347015, 2024). "Our initial findings showed a strong correlation between TMEM106B genetic variants and APOE mRNA levels, which suggest an involvement in Alzheimer’s disease." (PMID 38674351, 2024). "Apolipoprotein E (APOE) genetic variants are most notably known for their divergent impact on the risk of developing Alzheimer’s disease." (PMID 38216055, 2024). "Other animal studies have revealed that the introduction of APOE-ε4 in 5xFAD Alzheimer’s disease mice is linked to BBB impairment and decreased CBF, mediated by the up-regulation of cyclophilin-A-metalloproteinase-9 signaling within pericytes." (PMID 39596378, 2024). "Untargeted metabolomics identifies Lysophosphatidylcholines association with plasma Ptau181 levels and biological Alzheimer’s Disease in an APOE-ε4 dependent manner." (PMID 38260644, 2024). "The alleles account for six genotypes: APOE ε2/ε2, ε3/ε3, ε4/ε4, ε2/ε3,ε2/ε4 andε3/ε4).The APOE gene polymorphism is closely associated with Alzheimer’s disease (AD), the APOE ε2 allele is considered the most potent protective factor against AD." (PMID 39763652, 2024). "Human susceptibility to Alzheimer’s disease is linked to three apolipoprotein E (APOE) polymorphic alleles—E2, E3, and E4." (PMID 38396996, 2024). "The apolipoprotein E4 (APOE4) allele represents the major genetic risk factor for Alzheimer’s disease (AD)." (PMID 39056789, 2024). "Here the authors connect inherited Apolipoprotein E genotype with the risk of developing Alzheimer’s disease by demonstrating how, in an isoform- and lipidation-specific way, apoE modulates the aggregation, clearance and toxicity of Amyloid-beta." (PMID 38824138, 2024). "Dissociable effects of APOE ε4 carriage have been previously reported in the context of better attention despite the higher risk of Alzheimer’s disease." (PMID 38509472, 2024). "APOE encodes apolipoprotein E, a known genetic factor for Alzheimer’s disease and dementia with Lewy bodies." (PMID 38978726, 2024). "A case-control study has suggested an association between rs671 and Alzheimer’s disease, noting a synergistic effect of the rs671 variant and APOEε4, a missense variant of the apolipoprotein E gene, an established risk factor for Alzheimer’s disease." (PMID 39401906, 2024). "We found novel evidence that APOE ɛ4 worsened age-related ODI decreases in brain regions typically associated with atrophy patterns of Alzheimer’s disease." (PMID 38384997, 2024). "Apolipoprotein E ε4 allele (APOE4) is the predominant genetic risk factor for late-onset Alzheimer’s disease (AD)." (PMID 38206365, 2024). "Heterozygous carriers of the ɛ4 allele of the gene encoding ApoE are four times more likely to develop Alzheimer’s disease." (PMID 38665779, 2024). "Another significant aspect of AD is its multifactorial nature, with a notable genetic component, where the apolipoprotein E (APOE) gene and its alleles (APOE2, APOE3, and APOE4) serve as risk factors for Alzheimer’s disease." (PMID 38727281, 2024). "The apolipoprotein (APOE) epsilon 4 allele is the most common genetic risk factor for Alzheimer’s disease (AD), accounting for about 4% of Alzheimer’s disease variation." (PMID 39639910, 2024). "Three amyloid-β-predominant Alzheimer’s disease neuropathologic change-multiple system atrophy cases were available for genetic testing, and all carried the APOE ɛ4 allele." (PMID 38712319, 2024). "Beyond Alzheimer’s disease, APOE ε4 is also linked to mild cognitive impairment (MCI), typical aging, and other neurodegenerative conditions like Lewy body dementia (LBD) and vascular dementia (VD)." (PMID 39639910, 2024). "We evaluated the influence of APOE ε4 allele on synaptic density and investigated the effects of ε4 genotype on the associations of synaptic density with Alzheimer's disease (AD) biomarkers." (PMID 38477490, 2024).
Alzheimer disease (continued). "Apolipoprotein E (ApoE) ε4 carriers have a higher risk of developing Alzheimer's disease (AD) and show brain atrophy and cognitive decline even before diagnosis." (PMID 38376028, 2024). "In this study, our primary objective was to investigate the frequencies of common APOE gene SNPs (single nucleotide polymorphisms) associated with Alzheimer’s disease, specifically rs7412 and rs429358." (PMID 38790930, 2024). "Alzheimer’s disease (AD) risk is increased in carriers of the apolipoprotein E (APOE) ε4 allele and decreased in ε2 allele carriers compared with the ε3ε3 genotype." (PMID 38472178, 2024). "The strongest genetic risk factor for Alzheimer’s disease (AD) is the ε4 allele of apolipoprotein E (ApoE ε4)." (PMID 39506641, 2024). "We also apply the platform to investigate the role of APOE- ε4, a major risk variant for Alzheimer’s Disease, in its effect on neuronal survival." (PMID 37163077, 2024). "The e4 allele of the apolipoprotein E gene is the strongest genetic risk factor for sporadic Alzheimer’s disease." (PMID 38674351, 2024). "A third protein underlying the etiology of Alzheimer’s Disease, Apolipoprotein E, is a secreted lipoprotein involved in cholesterol metabolism." (PMID 39062996, 2024). "APOE polymorphic alleles represent the principal genetic determinants of Alzheimer’s disease, with the presence of APOEε4 being associated with heightened susceptibility to the onset of the condition." (PMID 38539669, 2024). "Modest differences in the associations of the APOE genotype have been reported between men and women for ischemic heart disease, Alzheimer’s disease, and lifespan, although the reasons underlying these differences are not known." (PMID 39286457, 2024). "One version, APOE ε4, has been found to increase the risk of Alzheimer’s Disease and has been studied alongside VEGF." (PMID 39698202, 2024). "Pertaining to its role in lipid metabolism and cholesterol homeostasis, APOE is the strongest genetic risk factor for Alzheimer’s disease (AD) and has been implicated in several metabolic, cardiovascular and other neurodegenerative diseases." (PMID 38216055, 2024). "Using this method, we compare the impact of ApoE isoforms which are known to bias the risk for Alzheimer’s disease." (PMID 39666759, 2024). "Single amino acid substitutions of these positions give rise to differences in the tertiary protein structure and function of apoE variants, as well as their role in disease, with apoE4 being the major risk factor for Alzheimer’s disease." (PMID 38641010, 2024). "The APOE gene and its variants have been linked to different types of dementia, including late-onset Alzheimer’s disease, vascular dementia, frontotemporal dementia, and Lewy body dementia (LBD)." (PMID 38542318, 2024). "The human APOE gene (h-APOE) has 3 naturally occurring alleles: ε3, the common allele; ε4, which increases Alzheimer’s disease (AD) risk up to 15-fold; and ε2, the rare allele which protects against AD." (PMID 38982272, 2024). "Among the multiple risk factors associated with the development of Alzheimer’s disease (AD), foremost is inheritance of one or both ε4 alleles of the apolipoprotein gene (APOE)." (PMID 38191671, 2024). "Individuals carrying the APOE ε4 allele are at risk of developing Alzheimer’s diseases (AD) as well as other forms of dementia." (PMID 38792885, 2024). "APOE ε2 is linked to impaired remyelination in MS but is protective against Alzheimer's disease (AD) and associates with higher myelin content." (PMID 39285941, 2024). "Noteworthy, the ε4 allele of ApoE, which is present in 15–20% of the population, represents the primary risk factor for late-onset Alzheimer Disease (AD), with a prevalence of 50–80% in AD patients." (PMID 38891031, 2024). "Apolipoprotein E4 (APOE4) is the strongest genetic risk factor for Alzheimer's disease (AD), yet it's unclear how this allele mediates risk." (PMID 39634654, 2024).